LRRC1 (leucine rich repeat containing 1)
Synonyms: LANO; dJ523E19.1; FLJ10775; FLJ11834
Tractability: Antibody: UniProt places it where antibodies can reach, with high confidence. PROTAC: ubiquitination databases record sites on it.
Gene: Protein-coding gene on chromosome 6 (53,794,497 to 53,924,125, forward strand). Ensembl gene ENSG00000137269.
Subcellular location: Cytoplasm; Membrane
Subcellular location (Human Protein Atlas): Cytosol
Pathways (Reactome):
Signal Transduction: RND2 GTPase cycle
Gene Ontology:
Cellular component: cytosol; cytoplasm; membrane
Genetic constraint (gnomAD): Loss-of-function variants: 15 observed, 35.91 expected, observed/expected ratio (o/e) 0.42, 90% interval 0.28 to 0.64. The upper end of that interval is the gene's LOEUF score, 0.64, which puts it in group 2 of 6, group 1 being the genes least tolerant of losing a copy. Missense variants: 355 observed, 413.98 expected, observed/expected ratio (o/e) 0.86, 90% interval 0.79 to 0.94. Synonymous variants: 155 observed, 167.52 expected, observed/expected ratio (o/e) 0.93, 90% interval 0.81 to 1.06.
Homologues: Orthologues: chimpanzee LRRC1 (99% identical), macaque LRRC1 (99% identical), pig LRRC1 (97% identical), mouse Lrrc1 (93% identical), rat Lrrc1 (93% identical), dog LRRC1 (85% identical), rabbit LRRC1 (83% identical), guinea pig LRRC1 (83% identical), tropical clawed frog lrrc1 (81% identical), zebrafish lrrc1 (61% identical). Paralogues in human: SCRIB (63% identical), LRRC7 (43% identical), ERBIN (42% identical), PHLPP2 (27% identical), PHLPP1 (26% identical), MFHAS1 (26% identical), SHOC2 (26% identical), LRRD1 (25% identical), LRRIQ4 (24% identical), PIDD1 (24% identical), LRRC40 (23% identical), LRRC8A (23% identical), and 19 more.
Diseases named in the same sentence as LRRC1 in open-access papers:
LRRC1 is named in the same sentence as 20 diseases in open-access papers, as found by Europe PMC text mining. Sharing a sentence is not in itself a finding about the gene and the disease. The quoted sentences say what the papers report.
hepatocellular carcinoma (6 papers, 2020 to 2025). A malignant tumor that arises from hepatocytes. "When overexpressed, LRRC1 reportedly enhanced hepatocellular carcinoma (HCC) cell growth and clonogenic activity, whereas its knockout had the opposite effect." (PMID 36370237, 2023). "At present, the precise mechanisms governing LRRC1 expression are incompletely understood, with one study of hepatoma cells having shown decreased promoter methylation to contribute to the epigenetic upregulation of this gene in these cells." (PMID 36370237, 2023). "One study reported that LRRC1 may be an oncogenic gene, and overexpression of LRRC1 accelerated the growth and colony formation of hepatoma cells." (PMID 34616724, 2021). "It is customarily considered that LRRC1 is conducive to hepatocellular carcinoma (HCC) development and may be a potential target for the treatment HCC17." (PMID 32978367, 2020). "This study aimed to elucidate the prognostic value of the leucine rich repeat containing 1 (LRRC1) gene in hepatocellular carcinoma (HCC) and to determine the effects of high and low LRRC1 expression on mutation and immune cell infiltration." (PMID 37505155, 2023). "LRRC1 can regulate downstream signaling through the C-terminal TSV sequence, the expression of which is higher in hepatocellular carcinoma tissues than in normal liver tissues, to promote tumor proliferation, invasion, and metastasis." (PMID 34760926, 2021).
cholangiocarcinoma (4 papers, 2021 to 2025). A carcinoma that arises from the intrahepatic biliary tree (intrahepatic cholangiocarcinoma) or from the junction, or adjacent to the junction, of the right and left hepatic ducts (hilar cholangiocarcinoma). "There is increasing evidence implicating LRRC1 in the progression of certain cancers, including cholangiocarcinoma, hepatocellular carcinoma, and acute myeloid leukemia (AML)." (PMID 40227650, 2025). "The promoting effect of circ-ZNF609 on cholangiocarcinoma is achieved via oncogene LRRC1 up-regulation through targeting miR-432-5p by endogenous competitive RNA mechanism." (PMID 34898474, 2021). "High expression of LRRC1 promoted malignant biological behaviors of tumor cells in cholangiocarcinoma." (PMID 34898474, 2021). "Down-regulation of miR-432-5p on cholangiocarcinoma proliferation, migration and invasion was partially reversed after transfection with si-LRRC1." (PMID 34898474, 2021). "Overall, YY1/eIF4A3/circ-ZNF609/miR-432-5p/LRRC1 have a significant role in progression of cholangiocarcinoma, and circ-ZNF609 is expected to become a novel biomarker for targeted therapy and prognosis evaluation of cholangiocarcinoma." (PMID 34898474, 2021). "Moreover, circ-ZNF609 promotes tumor progression in cholangiocarcinoma by upregulating LRRC1 via targeting miR-432-5p, leading to increased proliferation, migration, and invasion." (PMID 40227650, 2025). "Consistent with our findings, previous studies have demonstrated the oncogenic role of LRRC1 in HCC, NSCLC, and cholangiocarcinoma." (PMID 41369408, 2025).
lung carcinoma (4 papers, 2018 to 2025). "Tumor proliferation, invasion, and metastasis can be inhibited by knocking down LRRC1 to increase the efficacy of ensartinib in advanced lung cancer, as shown in non-small-cell lung cancer studies." (PMID 34760926, 2021). "In addition, abnormal expression of LRRC1 has been observed in various types of tumors, such as HCC, lung cancer, breast cancer, and so on." (PMID 38473980, 2024).
non-small cell lung carcinoma (4 papers, 2020 to 2023). A group of at least three distinct histological types of lung cancer, including non-small cell squamous cell carcinoma, adenocarcinoma, and large cell carcinoma. "High expression of LRRC1 is associated with advanced stage and decreased overall survival (OS) in patients with non-small-cell lung cancer." (PMID 34760926, 2021). "In non-small cell lung cancer cells, however, LRRC1 expression was reported to be post-translationally regulated by miR-193a produced by bone marrow MSCs." (PMID 36370237, 2023).
breast carcinoma (3 papers, 2022 to 2024). "For example, in one report, LRRC1 was found to regulate breast cancer stem cell fate determination, while it has also been shown to influence HCC cell growth and colony formation, and to contribute to NSCLC cell cisplatin resistance." (PMID 36370237, 2023). "Moreover, in LRRC1-knockout mice, LRRC1-deficiency induced higher levels of WNT ligand in breast cancer stem cells." (PMID 36370237, 2023).
acute myeloid leukemia (2 papers, 2025). Acute myeloid leukemia (AML) is a group of neoplasms arising from precursor cells committed to the myeloid cell-line differentiation. "For example, high LRRC1 levels in acute myeloid leukemia can promote the proliferation and glycolysis by upregulating the β-catenin/c-Myc axis." (PMID 41369408, 2025). "Moreover, upregulation of LRRC1 in acute myeloid leukemia cells could activate the β-catenin/c-Myc axis, thereby promoting the proliferation and glycolysis." (PMID 41369408, 2025).
alcohol abuse (1 paper, 2024). The use of alcoholic beverages to excess, either on individual occasions ("binge drinking") or as a regular practice. "The mRNA expression of LRRC1 was significantly increased (p < 0.001) in liver tissue from patients with hepatitis B virus (HBV) infection (GSE38941), alcohol abuse (GSE28619), or hepatitis C virus (HCV) infection (GSE6764) than in normal liver tissues." (PMID 38473980, 2024).
ischemic stroke (1 paper, 2021). A stroke disorder caused by obstruction of blood flow to the brain, due to thrombotic (local blood clot formation) or embolic (due to a blood clot or other material traveling from another site) event. "Whole-exome sequencing of 22 patients with familial aggregation of ischemic stroke identified LRRC1 single gene expression as an independent risk factor for stroke development." (PMID 34760926, 2021).
leukemia (1 paper, 2025). A malignant (clonal) hematologic disorder, involving hematopoietic stem cells and characterized by the presence of primitive or atypical myeloid or lymphoid cells in the bone marrow and the blood. "While PSMA3, LRRC1, HNRNPD, and FAM98A demonstrated strong binding to HHT in vitro using purified proteins, their weaker engagement in leukemia cellular models highlights fundamental differences between simplified biochemical systems and complex physiological environments." (PMID 41472850, 2025).
liver fibrosis (1 paper, 2024). "In the current study, we found that LRRC1 was upregulated in human and murine fibrotic liver tissues and positively associated with the severity of liver fibrosis." (PMID 38473980, 2024). "In summary, our current study firstly demonstrated the function and underlying mechanisms of LRRC1 in liver fibrosis." (PMID 38473980, 2024). "Herein, in the current work, we aimed to explore the role of LRRC1 in liver fibrosis and the underlying mechanisms involved." (PMID 38473980, 2024). "Furthermore, two murine liver fibrosis models were used to evaluate the associations between the expression of LRRC1 and ECM genes as well as α-SMA, the definitive marker of activated HSCs." (PMID 38473980, 2024). "Therefore, in the present work, we sought to explore the essential role of LRRC1 in the progression of liver fibrosis and the underlying mechanisms involved." (PMID 38473980, 2024). "A mechanistic study elucidated that the regulatory effect of LRRC1 on liver fibrosis is due to its ability to promote the stability of p-Smad2/3." (PMID 38473980, 2024). "More importantly, LRRC1 inhibition in vivo significantly alleviated CCl4-induced liver fibrosis by reducing collagen accumulation and hepatic stellate cells’ (HSCs) activation in mice." (PMID 38473980, 2024). "These collective findings provide compelling evidence that the downregulation of LRRC1 expression impedes the development of liver fibrosis." (PMID 38473980, 2024). "Our research revealed that LRRC1 was highly expressed in human and murine liver fibrotic tissues and positively correlated with the severity of liver fibrosis." (PMID 38473980, 2024). "Collectively, these results clarify a novel role for LRRC1 as a regulator of liver fibrosis and indicate that LRRC1 is a promising target for antifibrotic therapies." (PMID 38473980, 2024). "LRRC1 expression was positively correlated with liver fibrosis severity and significantly elevated in both human and murine fibrotic liver tissues." (PMID 38473980, 2024). "To explore the potential correlation between liver fibrosis and LRRC1 expression, we first analyzed the transcription level of LRRC1 using bulk gene expression data sourced from the National Cancer for Biotechnology Information Gene Expression Omnibus (GEO) database." (PMID 38473980, 2024). "More importantly, our data showed that inhibiting LRRC1 expression in vivo can alleviate liver fibrosis in a CCl4-induced mouse model, implying that LRRC1 could serve as a promising target for treating liver fibrosis." (PMID 38473980, 2024). "The HE, Sirius Red, and IHC staining results demonstrated that LRRC1 inhibition through AAV–shLRRC1 effectively alleviated CCl4-induced liver fibrosis, as evidenced by lower Ishak scores, a reduced Sirius-Red-stained area, and decreased α-SMA IHC scores compared to those in the CCl4+AAV–empty group." (PMID 38473980, 2024). "Therefore, we propose that the regulatory mechanism by which LRRC1 promotes liver fibrosis is a pathway shared across various etiologies." (PMID 38473980, 2024). "Thus, our findings contribute to the current knowledge on the mechanistic underpinnings of liver fibrosis and provide a reference for future functional studies on LRRC1." (PMID 38473980, 2024). "Third, although we successfully demonstrated the regulatory role of LRRC1 in liver fibrosis both in vitro and in vivo, further investigations employing LRRC1 knockout mouse models are necessary to comprehensively explore the biological significance of the inducible expression of LRRC1." (PMID 38473980, 2024). "Therefore, we speculated that LRRC1 may play regulatory roles not only in HSCs but also in hepatocytes, as well as in signaling crosstalk between HSCs and hepatocytes to promote liver fibrosis." (PMID 38473980, 2024). "However, whether LRRC1 is related to the process of liver fibrosis and the potential underlying mechanisms have not been determined." (PMID 38473980, 2024).
liver fibrosis (continued). "In addition, we also provided evidence showing that LRRC1 regulates HSC activation by stabilizing phospho-Smad2/3, thereby promoting the development of liver fibrosis." (PMID 38473980, 2024). "Furthermore, LRRC1 promoted HSC activation and liver fibrosis mainly by enhancing the stability of p-Smad2/3 via ubiquitination, thereby contributing to the activity of the TGF-β1/Smad pathway." (PMID 38473980, 2024). "However, the specific functions and mechanisms of LRRC1 in the progression of liver fibrosis have never been reported." (PMID 38473980, 2024).
preeclampsia (1 paper, 2024). Preeclampsia is a hypertensive disorder of pregnancy that is characterized by new-onset hypertension with proteinuria presenting after 20 weeks of gestation, and depending on mild or severe forms may initially present with severe headache, visual disturbances, and hyperreflexia. "Further studies are needed to elucidate LRRC1 ‘s precise role and therapeutic potential in preeclampsia." (PMID 39544937, 2024). "Consequently, elevated expression levels of LRRC1 may impede the cellular rearrangements necessary for modulating polarity, thereby influencing the pathogenesis of preeclampsia." (PMID 39544937, 2024). "The biomarkers CGB5, LEP, LRRC1, PAPPA2, and SLC20A1 offer varying prospects for predicting preeclampsia." (PMID 39544937, 2024). "Conversely, the roles of LRRC1 and SLC20A1 in preeclampsia remain unclear, necessitating further research." (PMID 39544937, 2024).
tumor (12 papers, 2017 to 2025). "Taken together, these data further confirm that LRRC1 drives tumor-induced angiogenesis via soluble mediators in the medium, indicating a pro-angiogenic role of LRRC1 in HCC." (PMID 41369408, 2025). "LRRC1 depletion inhibited the xenograft tumor growth of HL-60 cells in nude mice, and downregulated MACF1 expression as well as β-catenin/c-Myc signaling in tumor tissues." (PMID 40244019, 2025). "The present study concludes that miR-124-3 methylation is not only a potential diagnostic biomarker for early-stage OSCC but also acts as a tumor suppressor by directly targeting LRRC1, thereby inhibiting the proliferation and migration of OSCC cells." (PMID 40227650, 2025). "Through a series of experiments, including studies in xenograft mouse models and in vitro assays, we identify that LRRC1 is a potent tumor angiogenesis regulator." (PMID 41369408, 2025). "The mRNA levels of LRRC1 were significantly upregulated in HCC tissues compared with those in non-tumor tissues (p < 0.01)." (PMID 41369408, 2025). "To further investigate the clinical significance of LRRC1, we explored the TCGA database for identification of potential prognostic genes in HNSCC and our analysis reveals that LRRC1 expression was significantly higher in tumor tissues than in normal tissues." (PMID 40227650, 2025). "Our application of bioinformatics tools to investigate the tumor-suppressive mechanisms of miR-124-3 in OSCC identified LRRC1 as a potential target of miR-124-3." (PMID 40227650, 2025). "In vivo, LRRC1 promoted the formation of new blood vessels in the chick embryo chorioallantois membrane, together with tumor growth and angiogenesis in xenograft mice." (PMID 41369408, 2025). "LRRC1 is a regulator of cellular polarity that is expressed at high levels in a range of tumor tissue types." (PMID 36370237, 2023). "Concurrently, LRRC1 overexpression significantly enhanced tumor cell proliferation, migration and invasion, while knockdown of circ-ZNF609 partially inhibited these inhibitory effects." (PMID 34898474, 2021). "LRRC1 expression was dysregulated in the CCA tumor tissues and cells, and negatively correlated with miR-432-5p." (PMID 34898474, 2021). "The results manifested that miR-193a expression in NSCLC tumor tissues decreased while LRRC1 expression elevated relative to that in the adjacent normal tissues (both P < 0.05)." (PMID 32978367, 2020). "miR-193a and LRRC1 expression in NSCLC tumor tissues and adjacent normal tissues, and in DDP-resistant tissues and DDP-sensitive tissues were tested by western blot analysis and RT-qPCR." (PMID 32978367, 2020). "Our finding showed that up‐regulation of LRRC1 and down‐regulation of CYB5A were associated with tumor grade." (PMID 29123978, 2017). "Additionally, the remarkably elevated protein levels of LRRC1 in HCC tissues compared with those in the para-carcinoma tissues were validated (p < 0.01) through analyzing LRRC1 expression levels in tumor tissue microarray." (PMID 41369408, 2025). "Furthermore, we observed increased nuclear localization of β-catenin in tumor tissues from the LRRC1-OV group compared with the EV group (p < 0.05)." (PMID 41369408, 2025). "Moreover, overexpression of miR-124-3 suppressed the proliferation and migration of OSCC cells, while silencing the expression of LRRC1 produced similar tumor-suppressive effects." (PMID 40227650, 2025). "Similarly, LRRC1 has been shown to promote tumor progression in AML, with its knockdown inhibiting proliferation and glycolysis while promoting apoptosis." (PMID 40227650, 2025). "Furthermore, knockdown of LRRC1 expression led to tumor-suppressive effects similar to those induced by overexpression of miR-124-3 in OSCC." (PMID 40227650, 2025). "Interestingly, it was found that the tumor tissues from the LRRC1-OV group had more abundant blood vessels than those from the EV group." (PMID 41369408, 2025). "Tumor samples were divided according to high and low LRRC1 expression." (PMID 37505155, 2023).
tumor (continued). "The expression of LRRC1 was compared between HCC tumor and normal samples." (PMID 37505155, 2023). "This yielded 88 genes associated with tumor grade, in which seven DEGs (C8orf33, TSNAXIP1, TM4SF1, CTH, ANXA2, KIAA1522 and LRRC1) can distinguish HCC of G3 from G1, two DEGs (CYB5A and RRAGD) can distinguish HCC of G3 from G2, and two DEGs (CFHR4 and F13B) can distinguish HCC of G3 from G4." (PMID 29123978, 2017). "In vitro, LRRC1 overexpression significantly increased the mRNA, protein, and secretory levels of VEGFA and promoted tumor-induced migration, invasion, and tube formation of HUVECs." (PMID 41369408, 2025). "LRRC1 interacts with PDZ domain-containing proteins such as DLG1 CASK, MPP7, and SNX27, and thus participates in the homeostasis of epithelial tissues and tumor growth." (PMID 36370237, 2023). "In our study, analysis of public datasets reveals a positive correlation between LRRC1 and VEGFA, which drives us to hypothesize the linkage between LRRC1 and tumor angiogenesis." (PMID 41369408, 2025). "This suggests a model in which LRRC1 activates a parallel VEGFA/VEGFR2 axis that sustains angiogenesis and tumor growth even when primary pathways—such as RAF/MEK/ERK signaling or other receptor tyrosine kinases—are inhibited by sorafenib or other drugs, ultimately leading to treatment resistance." (PMID 41369408, 2025). "Coincidentally, the preliminary analysis of public datasets indicates a positive correlation between LRRC1 and VEGFA, prompting us to hypothesize and verify the linkage between LRRC1 and tumor angiogenesis." (PMID 41369408, 2025). "Meanwhile, LRRC1 enhances HCC cell proliferation in vitro and promotes tumor growth in vivo." (PMID 32213663, 2020). "Further mechanism studies showed that LRRC1 enhances PDK1 stability by promoting its deubiquitination via USP7, thereby increasing AKT1 phosphorylation levels and activating the AKT/GSK3β/β-catenin/VEGFA signaling pathway, ultimately accelerating tumor angiogenesis in HCC." (PMID 41369408, 2025).